ZBP1 (Z-DNA binding protein 1)
Diseases named in the same sentence as ZBP1 in open-access papers (continued):
Sharing a sentence is not in itself a finding about the gene and the disease.
tumor (continued). "The incorporation of CaO2 nanoparticles further alleviates tumor hypoxia, creating a favorable microenvironment for the synergistic effects of ROS modulation and ZBP1 regulation, thereby enhancing both tumor therapy and bone regeneration." (PMID 40908585, 2025). "This spatial distribution pattern aligns with ligand–receptor interaction models, indicating that ZBP1 likely modulates stromal–tumor cascade communication by regulating CAF chemokine secretion." (PMID 41430036, 2025). "Compared to WT controls, key proliferation-related pathways, including the G2/M checkpoint, E2F targets, and MYC targets, were significantly downregulated in Zbp1−/− tumor cells, indicating impaired cell cycle progression and proliferative capacity." (PMID 41430036, 2025). "ADAR1 loss-of-function or mutation results in the accumulation of endogenous Z-RNA, relieving ZBP1 inhibition and strongly driving ZBP1-dependent PANoptosis, which is critical for tumor immune editing and treatment resistance." (PMID 41583472, 2025). "ZBP1 deficiency reduces CCL7 expression in CAFs, diminishing their ability to promote tumor cell proliferation, migration, and invasion via the CCL7/CCR1 axis." (PMID 41430036, 2025). "Because PARP7i enhanced RT-induced necroptosis in vitro, we next tested the requirement for tumor-intrinsic ZBP1 in vivo." (PMID 41282221, 2025). "Gene Set Variation Analysis (GSVA) revealed marked transcriptomic reprogramming in Zbp1−/− tumor cells." (PMID 41430036, 2025). "In the same model, an intercalating agent that bypasses ADAR1 inhibition of ZBP1 to directly activate Z-DNA-dependent tumor cell death also improved the response to a checkpoint inhibitor." (PMID 40141064, 2025). "The current study extends this paradigm by revealing that in OSCC, ZBP1 indirectly activates the CCR1 pathway in tumor cells by regulating CCL7 expression in CAFs, enhancing their proliferation, migration, and invasion." (PMID 41430036, 2025). "The interplay between ADAR1 and ZBP1 is significant in the modulation of cellular death in neoplasms." (PMID 40422233, 2025). "The interferon response, induced by HSV-1-based OVs (oHSVs), can facilitate the accumulation of endogenous Z-RNA and subsequent activation of ZBP1-mediated PANoptosis to achieve an anti-tumor effect." (PMID 40721869, 2025). "Collectively, these findings suggest a potential tumor-type- or TME-dependent functional divergence of ZBP1." (PMID 41430036, 2025). "Utilizing single-cell transcriptomic data as a foundation, SCENIC analysis was conducted to investigate the impact of ZBP1 deletion on transcriptional regulatory networks within tumor cells." (PMID 41430036, 2025). "Exogenous CCL7 supplementation partially restores tumor growth in Zbp1−/− mice, indicating that ZBP1 bridges CAF–tumor cell communication through the CCL7–CCR1 axis." (PMID 41430036, 2025). "This study highlights ZBP1 as crucial for OSCC progression by regulating CCL7 expression in CAFs to activate CCR1 signaling in tumor cells." (PMID 41430036, 2025). "The increased expression of ADAR1-p150 in cancers restricts the interaction between ZBP1 and RIPK3, thereby suppressing ZBP1-mediated PANoptosis and facilitating tumor growth." (PMID 39966334, 2025). "This study not only enhances our understanding of macrophage‐mediated tumour immunity but also provides mechanistic insights into how ZBP1 integrates tumour‐intrinsic and immune‐regulatory pathways to influence HNSCC progression." (PMID 41299204, 2025). "Although ZBP1 was overexpressed in tumor tissues, high expression of ZBP1 was positively related to the immune response." (PMID 38684755, 2024). "To further explore the potential role of elevated ZBP1 and NLRP6 expression in oHSV infection in tumor cells, we generated ZBP1-deficient 4T1 and 4MOSC1 cells, as well as NLRP6-deficient 4T1 and 4MOSC1 cells, using CRISPR/Cas9-based gene editing." (PMID 38693119, 2024).
tumor (continued). "Our study also highlighted the significance of ZBP1-dependent necroptosis as an effector of MRE11–cGAS-mediated tumour suppression." (PMID 38200309, 2024). "The MC38 mouse model of colon cancer shows that the ZBP1-MLKL necroptotic cascade is essential for the anti-tumor effect of radiotherapy." (PMID 38523155, 2024). "Through a series of in vitro and in vivo experiments, we have demonstrated that ZBP1 overexpression enhances M1 polarization and subsequently suppresses tumor growth." (PMID 38369516, 2024). "The deletion of ZBP1 in MVT-1 cells has been demonstrated to block tumor necroptosis during tumor development and suppress metastasis, suggesting that ZBP1 plays a role in mediating tumor necroptosis during tumor development in preclinical cancer models." (PMID 39075259, 2024). "Further investigations manipulating cg09897064 methylation and ZBP1 expression through overexpression plasmids and shRNAs provided evidence for their role in modulating macrophage polarization and tumor growth." (PMID 38369516, 2024). "We found higher expression of ZBP1 in tumor tissue, but patients with higher expression had better prognosis." (PMID 39439891, 2024). "In this study, we have identified that oHSV primarily activates ZBP1 in tumor cells through the production of endogenous Z-RNA." (PMID 38693119, 2024). "By elucidating the molecular mechanisms involved, particularly the role of ZBP1 and cg09897064, our research provides potential targets for therapeutic interventions aimed at modulating macrophage polarization and inhibiting tumor growth." (PMID 38369516, 2024). "Here the authors show that HSV-1-based OV is capable of triggering ZBP1-mediated PANoptosis resulting in effective tumor growth inhibition." (PMID 38693119, 2024). "Western blotting analysis demonstrated that oHSV induced ZBP1-mediated PANoptosis in tumor cells, along with the release of immunogenic substances." (PMID 38693119, 2024). "This assessment was done to evaluate the possible roles of cg09897064 methylation and ZBP1 expression in macrophage M2 polarization-induced tumor growth." (PMID 38369516, 2024). "Their argument that ZBP1-mediated PCD served as a novel determinant of tumor immunogenicity masked by ADAR1flanks the possibility that ZBP1 has the potential to drive cancer immunity." (PMID 38553639, 2024). "The finding reveals that ZBP1-MLKL-mediated necroptotic signaling maximizes radiation-induced anti-tumor immunity through communications with the intrinsic STING pathway in tumor cells." (PMID 38323315, 2024). "Authors demonstrate that Z-DNA–binding protein 1 (ZBP1) mediates tumor necroptosis during tumor development in preclinical cancer models and ZBP1 deletion blocks tumor necroptosis and inhibits metastasis." (PMID 38994937, 2024). "Our findings suggest that oHSV-induced interferon response within tumor cells facilitates ZBP1-driven PANoptosis by elevating Z-RNA levels." (PMID 38693119, 2024). "In irradiated tumor cells, the ZBP1-MLKL necroptotic cascade induces cytoplasmic accumulation of mitochondrial DNA (mtDNA), which activates the cGAS-STING pathway, thereby enhancing the type I IFN response." (PMID 38523155, 2024). "In necrotic tumors, ZBP1 expression is notably elevated, and its deletion impedes tumor necrosis and apoptosis, ultimately inhibiting tumor cell proliferation, suggesting that ZBP1 provides a referenceable drug target for controlling tumor metastasis." (PMID 38553639, 2024). "ZBP1 inhibits M2 polarization and suppresses tumor growth, while cg09897064 methylation promotes M2 polarization and macrophage-induced tumor growth." (PMID 38369516, 2024). "In fact, research has found that the application of CBL0137, a small molecule that promotes the formation of Z-RNA in cells, can induce ZBP1-mediated necroptosis in tumor fibroblasts in melanoma." (PMID 38523155, 2024).
tumor (continued). "Specifically, we have discovered that ZBP1 promotes M1 polarization, while cg09897064 inhibits ZBP1 expression, leading to M2 polarization and tumor progression." (PMID 38369516, 2024). "An in vivo experiment was conducted to explore the influence of cg09897064 methylation and ZBP1 expression on the interactions between macrophage and tumor cells, particularly in terms of the promotion of tumorigenesis by M2 macrophages." (PMID 38369516, 2024). "Consistent with the findings in tumor cell lines, we also observed the upregulation of ZBP1 and NLRP6 in 4T1 tumors treated with oHSV." (PMID 38693119, 2024). "Our findings suggest that during HSV-1 infection, AIM2 expression is upregulated in some tumor cell lines (4MOSC1and 4MOSC2) but downregulated in others (SCC7, 4T1, and CT26), while ZBP1 expression is upregulated across all five tumor cell lines tested." (PMID 38693119, 2024). "In summary, this study reveals that oHSV likely activates ZBP1 in tumor cells primarily through the accumulation of endogenous Z-RNA." (PMID 38693119, 2024). "We observed that depletion of ZBP1 resulted in a significant reduction in the number of tumor cell deaths induced by oHSV compared to that in sgControl cells." (PMID 38693119, 2024). "Recent studies have shown that ZBP1 plays a key role in tumor necroptosis and that ZBP1 regulates tumor necroptosis in BC through the ZBP1-RIPK3 axis." (PMID 37771585, 2023). "Activated ZBP1 triggers the innate immune response, leading to the recruitment of immune cells for tumor infiltration." (PMID 37771585, 2023). "ZBP1 deletion prevents tumor cells from necroptosis during tumor formation, preventing tumor metastasis in the MVT-1 BC model." (PMID 37274025, 2023). "One study described the interaction of ADAR1 with ZBP1, identifying its role in cell death regulation and tumor." (PMID 38069556, 2023). "Zhang Ting’s team identified ZBP1 mediated necrosis as a new determinant of tumor immunogenicity masked by ADAR1." (PMID 37280687, 2023). "Subsequently, we conducted clustering and LASSO analysis on each tumor and found that the inhibitory and the stimulating immune checkpoints positively correlate with ZBP1, NLRP3, CASP1, CASP8, and TNFAIP3." (PMID 38002938, 2023). "ZBP1 was originally found as an up-regulated gene in the transcriptome study of tumor cells by interferon and named DLM-1." (PMID 37878133, 2023). "ZBP1 was initially identified in the tumor stroma and tumor cells as an IFN-inducible protein that senses Z-form nucleic acids, but was later confirmed in the cytosolic sensing of both DNA and RNA." (PMID 36845119, 2023). "In irradiated MC38 tumors, the ZBP1-mediated necroptotic signaling is crucial for anti-tumor immunity." (PMID 36142136, 2022). "ZBP1-mediated necroptosis can be enhanced via Caspase-8 gene ablation in tumor cells to improve the effects of radiotherapy." (PMID 36615244, 2022). "Recent research indicated that ZBP1 is highly increased in late stage of mouse and human tumors, and ZBP1 deletion inhibits tumor metastasis in pre-clinical cancer models." (PMID 35165523, 2022). "That is not only because of ZBP1-mediated tumor necroptosis but also attribute to mtDNA release via the necroptotic signaling." (PMID 36142136, 2022). "ZBP1-PANoptosome promotes tumor death and immune cell infiltration, and limits tumor volume and metastasis." (PMID 36142136, 2022). "For example, the inhibition of caspase-8 can significantly enhance activation of the ZBP1-MLKL pathway in tumor cells after radiotherapy and promote mitochondrial damage to release mtDNA." (PMID 35326602, 2022). "The study demonstrated that ADAR1 inhibits endogenous Z-RNAs and identifies ZBP1-mediated necroptosis as a novel determinant of ADAR1-masked tumor immunogenicity." (PMID 36204681, 2022). "ZBP1 was originally found to be significantly upregulated in mouse peritoneal tumor stromal cells or macrophages upon stimulation with IFN-γ or LPS." (PMID 36142136, 2022).
tumor (continued). "Recently, research has illustrated that ZBP1 is highly increased in mice and humans with late-stage tumours and that ZBP1 deletion inhibits tumour metastasis in preclinical cancer models." (PMID 36186436, 2022). "ZBP1-mediated PANoptosis is beneficial for eliminating infected cells and tumor cells, but abnormal or excessive PANoptosis can lead to a strong inflammatory response that is harmful to the host." (PMID 36142136, 2022). "The ZBP1-mtDNA binding initiates RIPK3-MLKL-dependent tumor necroptosis and blocks metastasis in the lung." (PMID 36142136, 2022). "Given the fact that tumor cells and infiltrating immune cells produce IFNs during tumor development, it is likely that the elevation of ZBP1 expression in tumors is achieved by IFNs induction." (PMID 33976222, 2021). "Particularly, our work identified ZBP1 as a potential target for inhibiting tumor necroptosis as a possible cancer therapy." (PMID 33976222, 2021). "ZBP1 expression was found to reduce tumor cell motility and chemotaxis, which decreased the potential of metastasis of tumor cells." (PMID 34867395, 2021). "The essentiality of Zα2 domain of ZBP1 in GD-induced necroptosis supports the idea that ZBP1 sense the cytosolic mtDNA to initiate tumor necroptosis." (PMID 33976222, 2021). "The story of ZBP-1 began in 1999 when it was identified as a novel gene upregulated in tumor stroma and activated macrophages and was called DLM-1." (PMID 32674269, 2020). "Z-DNA-binding protein 1 (ZBP1), alternatively known as DNA-dependent activator of IFN-regulatory factors (DAI) or Tumor stroma and activated macrophage protein (DLM1), plays a significant role in innate immune response against viruses or other non–self-agents." (PMID 33613567, 2020). "Of note, the RNA level of IGF2BP1 (IMP-1, CRD-BP, and ZBP-1) is highly upregulated in the tumor compared to muscle as well as bone." (PMID 25861239, 2015). "Collectively, these results demonstrate that spliceosome inhibitors can be used to generate Z-RNA and trigger on-demand ZBP1-dependent cell death in cells of the tumor microenvironment (TME) as a therapeutic strategy to enhance immunotherapy responses in resistant cancers." (PMID 41046514, 2025). "Again, this finding proved the tumour‐suppressive role of ZBP1 in HNSCC." (PMID 41299204, 2025). "Interestingly, Zbp1−/− tumor cells showed lower expression of H2afz, Nme1, Ran, and Ybx1, but higher expression of Nupr1 compared to WT cells." (PMID 41430036, 2025). "Differentially expressed genes (DEGs) between tumor cells from WT and Zbp1−/− mice were analyzed." (PMID 41430036, 2025). "The comprehensive role of ZBP1 in tumor immunomodulation remains inadequately understood." (PMID 41430036, 2025). "Notably, state 4 contained a higher proportion of WT-derived tumor cells, whereas state 5 was predominantly composed of Zbp1−/− derived tumor cells." (PMID 41430036, 2025). "To investigate whether ZBP1 modulates CCR1 expression in tumor cells via CCL7 produced by CAFs, we employed a co-culture system." (PMID 41430036, 2025). "A therapeutic target may be to sensitize tumor cells with agents that induce PANoptosis through activation of ZBP1, CASP8, RIPK3, or other key components." (PMID 40422233, 2025). "ZBP1-mediated PANoptosis plays an important role in the anti-tumor effects in various tumors." (PMID 40721869, 2025). "Z-DNA binding protein 1 (Zbp1), identified as an interferon (IFN)-induced tumor-associated protein, contains two left-handed helical nucleic acid-binding domains (Zα) and two RIP homotypic interaction motif (RHIM) domain that facilitates protein–protein interactions." (PMID 40307566, 2025). "A total of 431 wild-type (WT) and 275 Zbp1−/− tumor cells were examined." (PMID 41430036, 2025).
tumor (continued). "Abscopal-competent tumors were distinguished by enhanced type I IFN signaling, ZBP1 induction, and macrophage phagocytic activity at the irradiated site, coupled with systemic recruitment to distal tumor sites of antigen-presenting cells and effector T cell populations." (PMID 41282221, 2025). "Taken together, our findings proved the tumour‐suppressive role of ZBP1 in HNSCC." (PMID 41299204, 2025). "Notably, MOC1 transplantation models demonstrated significantly reduced tumor volumes in Zbp1−/− mice compared to wild-type (WT) controls." (PMID 41430036, 2025). "Our pseudotime analysis demonstrated that WT and Zbp1−/− tumor cells are positioned distinctly along the inferred trajectory, with WT tumor cells predominantly occupying early developmental states, while Zbp1−/− tumor cells are more prevalent at terminal states." (PMID 41430036, 2025). "Moreover, the study indicates that oHSV promotes the upregulation of ZBP1 expression in tumor cells by generating endogenous Z-RNA." (PMID 38693119, 2024). "According to the mRNA expression level in TCGA, FADD was related to lymph node metastasis, and ZBP1 might play a crucial role in tumor size as well as clinical stage." (PMID 38684755, 2024). "Expression of ZBP1 has been shown to be downregulated in tumor tissues." (PMID 39465258, 2024). "We found that ZBP1 expression is downregulated in tumor tissue." (PMID 39465258, 2024). "Additionally, in the B16-F10 and YUMMER1.7 mouse models of malignant melanoma, combined treatment with CBL0137 (an activator of ZBP1) and an anti-PD-1 antibody (an immune checkpoint inhibitor) has been found to induce tumor regression." (PMID 37328893, 2023). "However, tumor cells execute metabolic reprogramming to provide nutrients for proliferating cancer cells and possibly downregulate ZBP1 to prevent necroptosis." (PMID 37759572, 2023). "After collecting and processing the data in TCGA-KIRC database, the researchers compared the content of MYCN and other factors in normal kidney tissue and pathological tissue and found CDKN2A and ZBP1 in tumor tissues were up-regulated and MYCN was down-regulated." (PMID 37878133, 2023). "The ZBP1-PANoptosome also participates in tumor regression, and this process is regulated by an RNA modification enzyme, adenosine deaminase acting on RNA 1 (ADAR1), which contains the homologous Zα domain, through which it can bind with ZBP1 directly and block the sensor of intracellular Z-NA." (PMID 37895022, 2023). "It is therefore likely that the role of ZBP1 in cancer varies between tumor types or stages." (PMID 37450010, 2023). "However, in studies on breast cancer, promoter hypermethylation is found to lead to downregulation of ZBP1 expression, which promoted growth and migration of tumor cells." (PMID 37313458, 2023). "Therefore, CBL0137 generates a large amount of endogenous Z-DNA and induces ZBP1-dependent cell death in tumor stromal fibroblasts during ADAR1 inhibition." (PMID 36615244, 2022). "Knockdown of ZBP1 blocked tumor necroptosis during tumor development and inhibited metastasis." (PMID 35610275, 2022). "The role of ZBP1 remains ambiguous in tumor progression and metastasis." (PMID 35165523, 2022). "The ZBP1-mediated PANoptosis helps to remove invasive pathogens and uncontrolled tumor cells." (PMID 36142136, 2022). "The anti-tumor efficacy of radiotherapy may be related to the relationship between ZBP1-mediated necroptosis and the stimulator of the interferon genes (STING) pathway in tumors." (PMID 36615244, 2022).